UFM1 (ubiquitin fold modifier 1)
Diseases named in the same sentence as UFM1 in open-access papers (continued):
Sharing a sentence is not in itself a finding about the gene and the disease.
gastric cancer (continued). "We then investigated whether PDK1 could play a key role in UFM1-mediated gastric cancer metastasis inhibition." (PMID 31533855, 2019). "The invasion and migration abilities of gastric cancer cells with stable UFM1 overexpression were significantly decreased, and the gastric cancer cells with UFM1 stable knockdown showed the opposite results; similar results were also obtained in the nude mouse model." (PMID 31533855, 2019). "Further analysis revealed a low expression level of UFM1 in gastric cancer, which was positively correlated with the TNM staging and poor prognosis of patients, suggesting that UFM1 may be a potential tumor suppressor gene in gastric cancer." (PMID 31533855, 2019). "In the present study, we found that UFM1 was downregulated in gastric cancer tissue." (PMID 31533855, 2019). "Additionally, we analyzed the effect of the UFM1 expression on the prognosis of gastric cancer patients according to the TCGA database." (PMID 31533855, 2019). "Additionally, the effect of UFM1 on gastric cancer cell function is dependent on the expression of PDK1." (PMID 31533855, 2019). "Further analysis of related factors showed that the CDK5RAP3 and UFM1 coexpression was strongly linked to the invasive depth, lymph node metastasis and TNM stage, indicating that the two proteins are closely related to tumour invasion and migration in gastric cancer." (PMID 36387125, 2022). "In addition, we used immunohistochemistry to detect the expression of UFM1 in 120 paraffin-embedded tissues of gastric cancer and then analyzed the effect of its expression on the prognosis of gastric cancer patients." (PMID 31533855, 2019). "further found that UFM1 inhibited the expression of PDK1 via negative regulation of PI3K/AKT signaling, leading to suppression of invasive ability in gastric cancer." (PMID 39247188, 2024). "As a result, in clinical practice, the coexpression of CDK5RAP3 and UFM1 can be used in cooperation with TNM staging to effectively guide treatment and follow-up of patients with gastric cancer." (PMID 36387125, 2022). "Multivariate analysis indicated that the coexpression level of CDK5RAP3 and UFM1, as well as TNM stage were both independent predictive variables for patient prognosis with gastric cancer." (PMID 36387125, 2022). "In previous studies, we found that UFM1 can also negatively regulate PI3K/AKT signalling by increasing the ubiquitination of PDK1 to inhibit the invasion and metastasis of gastric cancer." (PMID 36387125, 2022). "This study mainly explored the impact of the coexpression level of UFM1 and CDK5RAP3 on the clinicopathological parameters of gastric cancer patients and its prognostic significance, providing a preliminary basis for further research." (PMID 36387125, 2022). "We compared the accuracy of CDK5RAP3 or UFM1 expression, as well as combined CDK5RAP3 and UFM1 expression and TNM staging, in predicting gastric cancer survival using ROC curve analysis." (PMID 36387125, 2022). "IHC staining of cancerous and paracancerous tissues from gastric cancer patient showed that CDK5RAP3 and UFM1 protein expression in cancerous samples were both lower than that in paracancerous." (PMID 36387125, 2022). "To investigate the potential role of UFM1 in the invasion and metastasis of gastric cancer, we constructed HGC-27 and AGS gastric cancer cell lines with stable overexpressing or downregulation of UFM1." (PMID 31533855, 2019). "Further studies have shown that UFM1 can inhibit the phosphorylation of AKT and downstream GSK3β by binding to PDK1 and increasing its ubiquitination, thereby inhibiting EMT of gastric cancer cells and exerting a tumor suppressor function." (PMID 31533855, 2019). "We used a Cox proportional hazards regression model to analyze the effects of UFM1 and PDK1 expression and other clinicopathological data on the prognosis of patients with gastric cancer." (PMID 31533855, 2019).
gastric cancer (continued). "Multivariate Cox regression analysis showed that co-expression of UFM1 and PDK1 and TNM stage were both independent predictors for gastric cancer." (PMID 31533855, 2019). "Moreover, in combination of UFM1, CDK5RAP3 and TNM (tumor, node, metastasis) stages increased the accuracy of prognosis prediction in gastric cancer patients." (PMID 39247188, 2024). "Interestingly, PDK1 abundance is controlled by the ubiquitin-fold modifier 1 (UFM1), a member of the ubiquitin-like protein (UBL) family, in gastric cancer cells, leading to PDK1 degradation." (PMID 35269443, 2022). "Therefore, in patients with gastric cancer, we assessed the relationship between relevant clinicopathological parameters and overall survival by detecting the CDK5RAP3 and UFM1 expression levels." (PMID 36387125, 2022). "Maybe it is possible to build a more precise model combining CDK5RAP3, UFM1 and TNM staging to predict 5-year survival of gastric cancer after surgery." (PMID 36387125, 2022). "Based on our previous study and an examination of public databases, this study found that the expression of the UFM1 and CDK5RAP3 genes are downregulated synchronously in gastric cancer patients with poor prognosis and that an interaction occurs between the UFM1 and CDK5RAP3 proteins." (PMID 36387125, 2022). "Therefore, we investigated the correlation between UFM1 and CDK5RAP3 expression and the prognosis of gastric cancer using public databases." (PMID 36387125, 2022). "In summary, our study shows that UFM1 may downregulate the expression level of PDK1, which inhibit the AKT/GSK3β pathway and downregulating the EMT activity of gastric cancer cells, leading to suppress the invasion and metastasis of gastric cancer cells." (PMID 31533855, 2019). "We also used Western blotting to detect CDK5RAP3 and UFM1 expression in the cancerous and paracancerous tissues of 43 gastric cancer patients and simultaneously detected the mRNA levels of CDK5RAP3 and UFM1 in the tumour tissues of 48 patients with gastric cancer." (PMID 36387125, 2022). "Using Western blot analysis, we confirmed that protein expression levels of UFM1 were significantly lower (n = 44, 41.9%) in tumor tissues compared with the corresponding adjacent nontumor tissues (n = 61, 58.1%) among 105 gastric cancer patients." (PMID 31533855, 2019). "UFM1, UfBP1, and CDK5RAP3 expression is also downregulated in gastric cancer compared with respective adjacent non-tumor tissues; this downregulation is a poor prognostic factor for affected patients." (PMID 37947621, 2023). "Although some studies have suggested that UFM1 binds to CDK5RAP3, the expression of the two proteins and their effects on the prolonged survival in gastric cancer have not been documented yet." (PMID 36387125, 2022).
Encephalopathy (6 papers, 2018 to 2026). Encephalopathy is a term that means brain disease, damage, or malfunction. "Genetic variants that hinder post-translational protein modifications by UFM1, UFMylation, cause encephalopathies." (PMID 41731076, 2026). "Our study unveils a pivotal role for UFMylation in neuronal development, provides a molecular understanding of the signaling mechanisms altered in UFM1-associated encephalopathies, and offers important insights into potential treatments for these disorders." (PMID 41731076, 2026). "Of note, variants in UBA5 and UFM1 in the same ufmylation pathway have also been described in patients with early-onset encephalopathy." (PMID 30552426, 2019).
diabetes (5 papers, 2014 to 2021). "Nonetheless, while some association between the UFM1 system and diseases such as cancer or diabetes could be established, many disorders caused by dysfunctional UFM1 enzymes were discovered to be of genetic origin." (PMID 33578803, 2021). "To investigate the role of Ufm1 in diabetes mice, we first analyzed the expression of Ufm1 and proinflammation cytokines (TNF-α, IL-6, and IL-1β) in db/db mice." (PMID 31829413, 2020). "The exact functions of UFM1 are poorly understood; however, it has been shown to be involved in heart disease and diabetes (conditions that present frequent comorbidity with depression), as well as schizophrenia." (PMID 27067128, 2016). "In this short review, we summarize the current state of Ufm1 research and its potential role in human diseases, like diabetes, ischemic heart disease and cancer." (PMID 24921187, 2014). "The up-regulated Ufm1 levels in diabetes may decrease the expression of LZAP leading to the activation of NF-κB pathway." (PMID 31829413, 2020). "Despite these researches, the biological function of Ufm1 still remains largely unknown, especially in macrophages and diabetes." (PMID 31829413, 2020). "In conclusion, the present study demonstrated that LPS induced the overexpression of Ufm1 through JNK/ATF2 and c-Jun pathway; the highly expressed Ufm1 further activated the NF-κB pathway and resulted in inflammatory response by decreasing LZAP expression in macrophage of diabetes." (PMID 31829413, 2020).
developmental delay (4 papers, 2016 to 2024). "A 1-Mb duplication in 13q13.3, including UFM1, was also identified in a case with global developmental delays, gait disturbance, and other abnormalities." (PMID 26872069, 2016). "Moreover, copy number variations in UBA5 or ubiquitin-fold modifier 1 gene (UFM1) were documented with the phenotypes of global developmental delays and gait disturbances in the ClinVar database." (PMID 26872069, 2016).
alcoholic hepatitis (3 papers, 2017 to 2024). Acute hepatitis resulting from ingestion of alcohol. "Ufm1 members have also been shown to be downregulated in alcoholic hepatitis and cirrhosis biopsies, and Ufl1 and Ufbp1, particularly, are suggested to act as tumor suppressors in certain cancers." (PMID 37131258, 2023). "The DNA methylation levels of Ufm1, Ufc1, and UfSP1 in the promoter CpG region were increased in the livers of alcoholic hepatitis patients." (PMID 28208700, 2017). "Previous studies showed that the expression of UFM1 is substantially decreased in MASH and alcoholic hepatitis (AH) patients’ biopsies, indicating a fundamental role of UFMylation in liver homeostasis." (PMID 39858578, 2024).
epilepsy (3 papers, 2018 to 2021). A brain disorder characterized by episodes of abnormally increased neuronal discharge resulting in transient episodes of sensory or motor neurological dysfunction, or psychic dysfunction. "A recently reported promoter mutation in UFM1 in the context of infantile encephalopathy with or without epilepsy is similarly predicted to only reduce but not eliminate transcription of an otherwise normal transcript." (PMID 29868776, 2018).
hepatocellular carcinoma (3 papers, 2021 to 2023). A malignant tumor that arises from hepatocytes. "The long non-coding RNA B3GALT5-AS1 suppresses hepatocellular carcinoma (HCC) cell proliferation, invasion, and metastasis by regulating miR-934 and UFM1." (PMID 37947621, 2023).
type 2 diabetes (3 papers, 2011 to 2020). "Ufm1 expression was elevated in the animal models of type 2 diabetes and ischemic heart injury that are associated with ER stress response." (PMID 23152784, 2012). "It has been reported that Ufm1 is up-regulated by ER stress induced diseases such as Type 2 diabetes and ischemic heart injury." (PMID 31829413, 2020). "There have been reports that Ufm1 is up-regulated in type 2 diabetes and ischemic heart injury, both pathological conditions which are associated with activation of ER stress response." (PMID 23152784, 2012). "UFM1 expression was 1.94 (protein) and 1.53 (mRNA) times higher in MKR mice (Type 2 diabetes model) than in wild type mice." (PMID 21494687, 2011).
cardiac hypertrophy (2 papers, 2023 to 2024). "To analyse the effects of Ufm1 overexpression on cardiac hypertrophy, we calculated the HW/BW ratio, hypertrophy and heart failure biomarkers." (PMID 37980507, 2023). "We observed that Tnfaip2 can be downregulated by ISO treatment in both Tg and NTg mice, and its expression in Tg-Ufm1 mice treated with ISO was lower than that in NTg mice, indicating that Tnfaip2 is a UFMylation-associated gene in ISO-induced cardiac hypertrophy." (PMID 37980507, 2023). "For instance, in mouse models of transverse aortic constriction-induced cardiac hypertrophy, both UFL1 and UFM1 are upregulated, activating protein UFMylation." (PMID 38233375, 2024). "In addition, the expression of Rpl26, a known substrate of UFMylation, was upregulated by ISO in NTg mice rather than in Tg-Ufm1 mice.These data indicated that Tnfaip2 may be a novel UFMylation-related gene that is associated with cardiac hypertrophy." (PMID 37980507, 2023). "However, overexpression of Ufm1 in hearts failed to vary ISO-induced HW/BW ratio and Acta1 increase, indicating that Ufm1 overexpression were not able to vary ISO-induced cardiac hypertrophy." (PMID 37980507, 2023).
depression (2 papers, 2016 to 2019). "Among them, ubiquitin-fold modifier 1 (UFM1) and eukaryotic translation initiation factor 4B (EIF4B) were highly upregulated in patients who developed IFN-α–induced depression." (PMID 31207337, 2019). "Among the most significant differentially expressed genes at baseline (predictors), we find upregulation of ubiquitin-fold modifier 1 (UFM1) and eukaryotic translation initiation factor 4B (EIF4B) in patients who later develop IFN-α-induced depression." (PMID 27067128, 2016).
ischemic heart disease (2 papers, 2014 to 2021). "A strong upregulation of Ufm1 was observed in a mouse model of ischemic heart disease that is induced by chronic inflammation." (PMID 24921187, 2014).
lymph node metastasis (2 papers, 2019 to 2022). "Univariate analysis showed that depth of invasion, lymph node metastasis, TNM stage, distant metastasis, UFM1 expression, PDK1 expression, and combined with UFM1 and PDK1 expression were closely related to patient prognosis." (PMID 31533855, 2019).
Obesity (2 papers, 2010 to 2024). Accumulation of substantial excess body fat. "As expected, the expression levels of hepatic Uba5, Ufc1, Ufl1, and Ufm1 are significantly reduced in patients with obesity, MASLD, and MASH by analyzing the public data sets." (PMID 39858578, 2024).
oral squamous cell carcinoma (2 papers, 2023 to 2025). "Higher expression of UFM1 was found in oral squamous cell carcinoma (OSCC), and its overexpression was associated with shorter overall survival, suggesting that UFM1 may be a poor prognostic factor for OSCC." (PMID 41179291, 2025). "However, the roles and pathways of UFM1 in oral squamous cell carcinoma (OSCC) has remained undefined." (PMID 37980168, 2023).
acute kidney injury (1 paper, 2024). Sudden and sustained deterioration of the kidney function characterized by decreased glomerular filtration rate, increased serum creatinine or oliguria. "Our study further corroborates these findings, showing a reduction in DDRGK1, UFL1, and UFM1 in acute kidney injury, which suggests a decrease in ER-phagy." (PMID 38233375, 2024).
anemia (1 paper, 2021). A reduction in the number of red blood cells, the amount of hemoglobin, and/or the volume of packed red blood cells. "Additionally, no severe anemia was observed in adult Cdk5rap3 conditional KO mice (our unpublished observation), suggesting that unlike other components of the Ufm1 system, Cdk5rap3 is not essential for red blood cell development." (PMID 33504792, 2021).
cardiomyopathy (1 paper, 2023). A disease of the heart muscle or myocardium proper. "Such ideas are consistent with the documented phenotypes related to ER‐stress in cell lines lacking UFM1 pathway components or in phenotypic observations of UFM1‐linked morbidities that are plausibly ER‐stress driven (e.g. cardiomyopathy, defective haematopoiesis and skeletal dysplasia)." (PMID 36680403, 2023).
cerebellar ataxia (1 paper, 2016). A neurological syndrome characterized by clumsy and uncoordinated movement of the limbs, trunk, and cranial muscles. "The finding of a UBA5 mutation in cerebellar ataxia suggests that impairment of the UFM1 pathway may contribute to the neurological phenotypes of ARCA." (PMID 26872069, 2016).
colorectal cancer (1 paper, 2012). A primary or metastatic malignant neoplasm that affects the colon or rectum. "In addition to endogenous Ufm1, this antibody detected extra bands, including 28 kDa, 34 kDa, 45 kDa, 52 kDa and 70 kDa in colorectal cancer cell HCT116." (PMID 23152784, 2012).
diffuse large B-cell lymphoma (1 paper, 2016). "However, despite the amplification of UFC1 in pancreatic adenocarcinoma and amplification of both UFC1 and UFL1 in diffuse large B-cell lymphoma, high percentage of UFL1 deletion and UFL1/UFM1 deletion was also detected in pancreatic adenocarcinoma and diffuse large B-cell lymphoma, respectively." (PMID 27212118, 2016).
Down syndrome (1 paper, 2023). "Interestingly, UFM1, UFL1, and CDK5RAP3 are all key components of the UFMylation pathway which is an ubiquitin-like posttranslational protein modification, while TTC3 is an E3 ubiquitin ligase highly expressed in the CNS and is closely involved in Down syndrome." (PMID 36917672, 2023).
endotoxemia (1 paper, 2025). "Deficiency of Ufl1 or Ufm1 in mice shows a significantly attenuated inflammatory response in LPS‐induced endotoxemia, alum‐induced peritonitis and E. Coli‐induced sepsis." (PMID 39985286, 2025). "It is further demonstrated that myeloid cell‐specific Ufl1 or Ufm1 deficiency in mice significantly alleviated inflammatory responses and tissue damage following lipopolysaccharide (LPS)‐induced endotoxemia and alum‐induced peritonitis." (PMID 39985286, 2025). "Myeloid cell‐specific deletion of Ufl1 or ubiquitin‐fold modifier 1 (Ufm1) significantly alleviates inflammatory responses in LPS‐induced endotoxemia and alum‐induced peritonitis." (PMID 39985286, 2025).
frontotemporal dementia (1 paper, 2024). Frontotemporal dementia (FTD) comprises a group of neurodegenerative disorders, characterized by progressive changes in behavior, executive dysfunction and language impairment, as a result of degeneration of the medial prefrontal and frontoinsular cortices. "Futures studies should also analyze UFM1 and UFSP2 in non-tau neurodegenerative diseases such as frontotemporal dementia and Lewy body disease to test whether the UFMylation changes are specific for AD or for tauopathies in general." (PMID 39696466, 2024).
gastric tumor (1 paper, 2019). "Expression of UFM1 in gastric tumor and paired adjacent noncancerous tissues from 437 patients was analyzed by Western blotting, immunohistochemistry, and realtime PCR." (PMID 31533855, 2019).
Huntington disease (1 paper, 2026). Huntington disease (HD) is a rare neurodegenerative disorder of the central nervous system characterized by unwanted choreatic movements, behavioral and psychiatric disturbances and dementia. "Fusion of UFM1ΔC4 to p622KR (p622KR-UFM1ΔC4) restores the p62-mediated pathogenic autophagic degradation in primary cortical neurons and Huntington's disease mouse striatum." (PMID 42212323, 2026).
hypomyelinating leukodystrophy 14 (1 paper, 2023). "UFM1 (OMIM: #610553) is associated with hypomyelinating leukodystrophy 14 (HLD14, OMIM: #617899)." (PMID 38079206, 2023).
Infantile encephalopathy (1 paper, 2018). Encephalopathy with onset in the infantile period. "Similar to our previous work on UBA5-related severe infantile encephalopathy, we show that mutations in UFM1 itself as well as in UFC1, encoding the sole E2 conjugating enzyme for UFM lead to widespread impairment of ufmylation." (PMID 29868776, 2018).
insulinoma (1 paper, 2011). "To address this, we investigated the role of UFM1 and UFBP1 on insulin secretion in the rat glucose-responsive insulinoma cell line INS1-832/13." (PMID 21494687, 2011).